CSPG4 (chondroitin sulfate proteoglycan 4)
Diseases named in the same sentence as CSPG4 in open-access papers (continued):
Sharing a sentence is not in itself a finding about the gene and the disease.
breast carcinoma (continued). "It will be interesting to find out whether there is a correlation between CSPG4 expression level and the outcome, which can be examined later when sufficient outcome data are available from the TCGA breast cancer project." (PMID 22984505, 2012). "The expression of CSPG4 in breast cancer has been reported very recently." (PMID 21658254, 2011). "Hence, counteracting CSPG4-CAR-T cells in TNBC via down-regulating CSPG4 might impair metastasis formation and stunt breast cancer progression." (PMID 31779130, 2019). "Therefore, CSPG4-CAR-T cells could launch a dual attack on bulk breast cancer cells and on the tumor-protective TME." (PMID 31779130, 2019). "Although CSPG4 expression does not appear to be expressed exclusively by basal breast cancers including TNBCs, its expression may be associated with poor prognosis and relapse in breast cancers." (PMID 29375561, 2017). "As expected, the growth of CSPG4-negative breast cancer spheroids was unaffected by CAR-MαCSPG4, showing that CSPG4-targeting CAR-Ms specifically regulated the growth of CSPG4-expressing cancer cells." (PMID 40082557, 2025). "The high expression level of CSPG4 in TNBC was confirmed through analyzing the TCGA-BRCA dataset, showing that CSPG4 expression was higher in BLBC/TNBC than other subtypes of breast cancer." (PMID 35280756, 2022). "To further investigate the expression of PDL1 and CSPG4 in TNBC cells, we analyzed their protein levels in several breast cancer cell lines by immunoblotting and flow cytometry." (PMID 35280756, 2022). "Strikingly, CSPG4 expression exhibited a clear preponderance to TNBC, with few ER+ or Her2+ (EGFR2) breast cancer subtypes expressing CSPG4." (PMID 31779130, 2019). "In order to establish a translational relevance, we examined the expression of CSPG4 and CHST11 in specimens from breast cancer patients to compare the level of expression of these genes between normal and malignant tissues." (PMID 21658254, 2011). "Chondroitin sulfate proteoglycan 4 (CSPG4) has been demonstrated to exhibit aberrant expression in various tumor types, including soft tissue sarcoma, squamous cell carcinoma of the head and neck, breast cancer, and anaplastic thyroid cancer." (PMID 38015710, 2023). "The CSPG4 protein (non-glial antigen) is expressed as a cell surface proteoglycan by basal breast carcinoma cells." (PMID 35145999, 2022). "Chondroitin sulfate proteoglycan 4 (CSPG4, also known as neuron-glial antigen-2, NG2) is a type of single transmembrane protein that is expressed on a variety of tumors, including melanoma, breast cancer, malignant gliomas and leukemia." (PMID 33643279, 2020). "Additionally, a special subpopulation of stromal cells characterized by Nestin, CSPG4, α-smooth muscle actin, and PDGFR-α expression are recruited to the TME by breast cancer cells." (PMID 31779130, 2019). "Transient transfection of the human breast cancer cell line MDA-MB-231 with the siRNAs for carbohydrate (chondroitin 4) sulfotransferase-11 (CHST11) and chondroitin sulfate proteoglycan 4 (CSPG4 ) was used to investigate the involvement of these genes in expression of surface P-selectin ligands." (PMID 21658254, 2011). "As expected, we did not detect binding to IGROV1 ovarian or SKBR3 breast cancer cells (neither express CSPG4, but overexpress tumor antigens FRα and human epidermal growth factor receptor 2 (Her2), respectively, confirmed by binding of target antigen-specific IgEs)." (PMID 37185332, 2023). "While CSPG4 IgE triggered significant degranulation in the presence of WM1366 cells expressing intermediate levels of CSPG4, the antibody did not trigger degranulation in the presence of low target-expressing WM1361 cells or non-CSPG4-expressing SKBR3 breast cancer cells." (PMID 37185332, 2023).
breast carcinoma (continued). "However, how CSPG4 leads to adverse clinical outcomes of advanced breast cancers is still not known and will be an interesting topic to investigate." (PMID 35280756, 2022). "The CSPG4, which is also known as non-glial antigen or its also known as melanoma chondroitin sulfate proteoglycan, is a cell-surface proteoglycan exhibited by basal breast carcinoma cells." (PMID 32245065, 2020). "TNBC accounts for up to 20% of breast cancer cases and despite its heterogeneity, three receptors are commonly overexpressed, namely the EGFR1 (in up to 70% of TNBC cases), the epithelial cell adhesion molecule (EpCAM) and chondroitin sulfate proteoglycan 4 (CSPG4)." (PMID 31756933, 2019). "The resulting αCSPG4(scFv)-MAP tau was similarly evaluated for binding and internalization in CSPG4+ human triple-negative breast cancer (TNBC) cell lines, alongside CSPG4− mammary carcinoma lines." (PMID 28657611, 2017).
glioblastoma (56 papers, 2011 to 2025). The most malignant astrocytic tumor (WHO grade IV). "Chondroitin sulfate proteoglycan 4 (CSPG4) is highly expressed in different solid tumors including glioblastoma, where CSPG4 expression is associated with more aggressive disease." (PMID 31798595, 2019). "NG2/CSPG4 is a complex surface-associated proteoglycan (PG) recognized to be a widely expressed membrane component of glioblastoma (WHO grade IV) cells and angiogenic pericytes." (PMID 24386429, 2013). "In parallel, fixed multipeptide vaccines like IMA950, which targets a fixed set of glioblastoma-associated antigens (e.g., BCA, CSPG4), are also being explored in combination with checkpoint inhibitors." (PMID 41441679, 2025). "Above all this, CSPG4 has been employed as a CAR-T therapy target in various types of malignancies including glioblastoma and B-cell precursor leukemia, which highlights the importance of this target antigen for different types of immunotherapies." (PMID 38146364, 2023). "In orthotopic a glioblastoma neurosphere xenograft model, intracranial injection of CSPG4 CAR T cells has been demonstrated to halt tumor progression." (PMID 36721153, 2023). "The expression of CSPG4 has been reported in different oncological indications, including ovarian cancer, breast cancer, glioblastoma, etc., which renders this antigen as an interesting target antigen in targeted immunotherapy." (PMID 38146364, 2023). "They generated glioblastoma CSCs from resected human tumors and indicated that anti‐CSPG4 CAR‐ T‐cells have significant capability to recognize and eliminate these cells." (PMID 37698048, 2023). "It is reported for the first time that CSPG4 is expressed on glioblastoma cancer stem cells (GSC) and demonstrate that anti‐CSPG4 CAR‐transduced T cells recognize and kill these GSC." (PMID 34585512, 2021). "For instance, over 60% of patients with glioblastoma (GBM) overexpress CSPG4, thereby serving as an important prognostic factor." (PMID 34944101, 2021). "For instance, the expression of CSPG4 might be an important prognostic factor in glioblastoma multiforme (GBM), where it is associated with enhanced tumor progression and resistance to radiotherapy." (PMID 32019907, 2020). "Other antigens that were proposed as targets for CAR-T cell approaches in glioblastoma are EphA2, CSPG4, CD133, and CD70." (PMID 31798595, 2019). "In the following we will discuss the merits and challenges of CSPG4 as a target for the CAR-T-cell therapy of glioblastoma." (PMID 31779130, 2019). "CAR-T cells with CSPG4-specific second- or third-generation CARs, among other cancer entities, also lysed CSPG4-positive glioblastoma cells, including GB stem-like cells." (PMID 31798595, 2019). "NG2/CSPG4 expression has been demonstrated in oligodendrogliomas, astrocytomas, and glioblastomas (GB), and it correlates with malignancy." (PMID 30213051, 2018). "Anti-CSPG4 CAR T cells efficiently controlled the growth of glioblastoma cells in vitro and in vivo upon intracranial inoculation." (PMID 30279357, 2018). "A new relevance from preclinical studies using an anti-NG2/CSPG4 CAR-T therapy in glioblastoma (GB) has been recently emphasized." (PMID 30213051, 2018). "Of the 6 glioblastoma cell lines assayed, 3 demonstrated CSPG4 expression, as did 2 of the 4 triple-negative breast cancer cell lines." (PMID 25197555, 2014). "In light of these studies, we interrogated multiple single-cell RNAseq datasets from pediatric diffuse midline gliomas (DMG) and adult IDH1 wild-type glioblastomas (GBM) to curate a list of mechanosensitive ion channels that are expressed in OPC-like cells also expressing CSPG4." (PMID 40791371, 2025). "Further, in glioblastoma tissue and tumor-associated vasculature, CSPG4 is highly expressed with minimal heterogeneity but is not detected in the normal brain parenchyma." (PMID 36721153, 2023). "Beard et al131 reported for the first time that glioblastoma CSCs express CSPG4 on their surface." (PMID 37698048, 2023).
glioblastoma (continued). "Expression of CSPG4 predicted poor survival and resistance to ionizing radiation in glioblastoma." (PMID 35501919, 2022). "CSPG4 is as a marker for glioblastoma stem cells (GSCs), which are instrumental in GBM progression." (PMID 31779130, 2019). "Additionally, intracranial application of CSPG4-CAR T cells in a murine model of glioblastoma imposed efficient tumor control." (PMID 31195686, 2019). "Additionally, glioblastoma stem cells were generated from resected human tumors, and CSPG4 expression was determined by RT-PCR and FACS." (PMID 25197555, 2014). "Interestingly, the majority of the immunolocalized NG2/CSPG4 isoforms present in glioblastoma tissue were present in foetal brain, except for one isoform that seemed to be exclusive of tumour cells, being absent in foetal brain." (PMID 24386429, 2013). "CSPG4 CAR-T cells exhibited potent inhibitory effects on a glioblastoma neurosphere (GBM-NS) model in vitro and in vivo." (PMID 39506843, 2024). "CAR T cells targeting B7-H3, CSPG4 and HER2 have also been shown to eliminate both differentiated glioblastoma and glioblastoma-initiating cells." (PMID 36721153, 2023). "The chondroitin sulfate proteoglycan 4 (CSPG4) antigen also known as MCSP is strongly expressed on 90% of melanoma cancer cell lines, and other tumors such as glioblastoma, sarcoma, and leukemia." (PMID 34207884, 2021). "In human glioblastoma cells, NG2/CSPG4-mediated activation of integrin signaling promotes cell survival through sustained activation of Akt (protein kinase B) and chemoresistance through integrin-dependent PI3K/Akt signaling." (PMID 29196603, 2018). "On glioblastoma tissue, prototype mAb 2161D7, and clone 2164G7 belonging to the same class, again revealed pericyte-specific NG2/CSPG4 isoforms." (PMID 24386429, 2013). "Additionally, glioblastoma CSCs have been reported to transform into vascular pericytes, and angiogenic vessels in GBM tissue demonstrate the expression of CSPG4." (PMID 34944101, 2021). "Furthermore, we report for the first time that CSPG4 is expressed on glioblastoma cancer stem cells (GSC) and demonstrate that anti-CSPG4 CAR-transduced T cells recognize and kill these GSC." (PMID 25197555, 2014).
glioma (33 papers, 2013 to 2025). A benign or malignant brain and spinal cord tumor that arises from glial cells (astrocytes, oligodendrocytes, ependymal cells). "In gliomas, the expression of chondroitin sulfate proteoglycan 4 (CSPG4, also known as NG2) is inversely linked with patient survival." (PMID 36721153, 2023). "Furthermore, NG2/CSPG4-expressing cells are the most important population of cycling cells in the adult CNS and gene mutations can accumulate, leading to glioma tumorigenesis." (PMID 35891187, 2022). "Following treatment with 4-AP, glioma cell conditioned medium was collected, concentrated and profiled by CSPG4 western blot." (PMID 40791371, 2025). "To further validate this data, we conducted cell-attached patch clamp recordings in CSPG4 knockout glioma cells." (PMID 40791371, 2025). "We observed that glioma cells constitutively shed CSPG4 into their culture medium, a process inhibited by brief treatment with ADAM10 inhibitor GI254023X (5 μM, 15 mins)." (PMID 40791371, 2025). "We analyzed these cells for the expression of neural/stem precursor cell markers (OLIG1, OLIG2, CSPG4/NG2, NESTIN), which are also transcription factors and lineage markers associated with glioma stem cells (GSC), and DMRTA2." (PMID 38509074, 2024). "CSPG4/NG2 was intensively studied in connection with gliomas and other tumors where it induces cell proliferation and migration and its expression correlated with malignancy." (PMID 38107409, 2023). "A study demonstrated in vivo therapeutic effects of intracranial delivery of chondroitin sulfate proteoglycan 4 (CSPG4)-CAR T-cells in nude mice transplanted with CSPG4-expressing glioma cells or GBM neurospheres models." (PMID 35936003, 2022). "As a whole, all these observations are in line with most gliomas originating from the subcortical white matter rich in immature cells expressing NG2/CSPG4." (PMID 35891187, 2022). "This is consistent with the origin of most gliomas from the subcortical white matter that is rich in OPCs expressing NG2/CSPG4, platelet-derived growth factor alpha (PDGFRα), and oligodendrocyte lineage transcription factor 2 (Olig2)." (PMID 32599896, 2020). "In the present study, we analyzed the role of NG2/CSPG4 in relation to the origin, progression, and prognosis of 61 adult gliomas." (PMID 32599896, 2020). "In the present study, we confirm an inter-grade NG2/CSPG4 variability in gliomas and its correlation with the malignancy grade, in agreement with previous findings." (PMID 32599896, 2020). "Intracranial delivery of CSPG4-CAR-T cells was effective in vivo in nude mice transplanted with CSPG4-expressing glioma cells or neurospheres." (PMID 33154756, 2020). "Unlike our previous study showing syndecan 1 to be the main VAR2CSA receptor in the placental syncytium, we found several interesting hits on the glioma cell lines, including syndicans, glypicans, neuropilins, decorin, versican, CSPG4, and PTPRZ1." (PMID 31466397, 2019). "NG2/CSPG4+ cells in gliomas conditions poor survival as they promote cell proliferation and motility via β1 integrins and growth factors." (PMID 30213051, 2018). "This casts some doubts on the possibility to employ anti-NG2/CSPG4 antibodies in the therapy of gliomas or, at least, via a systemic administration." (PMID 30213051, 2018). "First we investigated the efficacy of the combination treatment in eradicating U87MG gliomas that are 99.2±0.2 % (n=3) NG2/CSPG4 positive, as recognized by mAb9.2.27." (PMID 24127551, 2013). "Next, we investigated whether the knockout of the CSPG4 gene directly affects the growth of glioma cells using CSPG4 KO glioma cells and assessed cancer cell growth over time using the CellTiterGlo assay." (PMID 40791371, 2025). "We next investigated whether the observed interaction between NLGN3 and CSPG4 is necessary for the NLGN3-induced changes in glioma, such as glioma proliferation and growth." (PMID 40791371, 2025).
glioma (continued). "Having established that PIEZO1 is a primary actuator responsible for NLGN3-mediated shedding of CSPG4, we hypothesized that blocking the PIEZO1 response in glioma would mimic loss of microenvironmental NLGN3 and affect glioma growth in vivo." (PMID 40791371, 2025). "We hypothesized that shed NLGN3 subsequently triggers CSPG4 shedding from the membrane of glioma cells and OPCs in an autocrine and/or paracrine fashion." (PMID 40791371, 2025). "Moreover, CSPG4 was also found in a broad range of other malignancies such as triple-negative breast cancer, various types of gliomas, head and neck squamous cell carcinoma, soft-tissue sarcomas, tumor-associated vasculature and also leukemia." (PMID 37901209, 2023). "Additionally, a limited number of CSC markers are currently available but their biological function needs to be fully characterized, such as CSPG4 in multiple cancer types, EGFRvIII and IL13Rα2 in gliomas, and EpCAM in prostate cancer." (PMID 33806296, 2021). "NG2/CSPG4 expression has been found to be widespread in murine gliomas." (PMID 30213051, 2018). "In summary, NG2/CSPG4 expression can be considered as variable in human gliomas." (PMID 30213051, 2018). "In others’ experience, NG2/CSPG4+ cells in the gray and white matter of normal brain are demonstrable only after prolonged incubations and increased antibody concentrations in comparison with glioma tissue." (PMID 30213051, 2018). "Before the discovery of NG2/CSPG4, CS could be biochemically and histochemically demonstrated in gliomas, together with GAGs." (PMID 30213051, 2018). "Indeed, we observed a significant reduction in the growth rate of CSPG4 KO glioma cells in neurosphere monoculture from day 3 onwards, indicating that CSPG4 may play a cell-intrinsic role in maintaining stem-like glioma neurospheres." (PMID 40791371, 2025). "Therefore, we sought to determine whether shed ectodomains of NLGN3 and CSPG4 are detectable in cerebrospinal fluid (CSF) of human glioma patients." (PMID 40791371, 2025). "Moreover, GIC differentiation increases the drug sensitivity, and thus, the strategy of the induction of the differentiation by the downregulation of the CS modification on CSPG4 may be utilized in the effective mobilization therapy of glioma." (PMID 38309500, 2024). "Therefore, targeting CSPG4 could have direct effects on glioma stem cell maintenance/differentiation." (PMID 38309500, 2024). "Chondroitin sulfate proteoglycan 4 (CSPG4) is a surface type I transmembrane core proteoglycan that is important in cell survival, migration, and angiogenesis and has been associated with the progression and metastasis of tumors, such as gliomas and soft tissue sarcomas." (PMID 36292695, 2022). "Hence, the capture of glioma CTC might be useful for predicting response to anti-CSPG4 CAR-T therapy." (PMID 31466397, 2019). "Our findings have greater implications beyond the elucidation of NG2/CSPG4 as a therapeutic target, but demonstrate a proof of concept that mAb9.2,27 could activate cytotoxic functions of glioma infiltrated microglia/macrophages that may further hold therapeutic potential." (PMID 24127551, 2013). "More broadly, our findings underscore the therapeutic potential and relevance of ECM components such as GPC2, CSPG4, and PTPRZ1 as novel pan-glioma immunotherapy targets." (PMID 40517137, 2025). "In gliomas, reactive astrocytes, some tumor cells, vascular pericytes, ECs, normal neurons, and macrophages expressed NG2/CSPG4 in the cytoplasm and/or on the cell membrane." (PMID 32599896, 2020). "In rat gliomas, transplacentally induced by N-ethyl-N-nitrosourea (ENU), NG2/CSPG4 was found to be diffuse in oligodendrogliomas, where cells failed to differentiate into mature oligodendrocytes." (PMID 30213051, 2018). "In human gliomas, there are too few studies concerning NG2/CSPG4 correlation with survival and with chemo- and radiotherapy." (PMID 30213051, 2018).